ASXL2 (ASXL transcriptional regulator 2)
Diseases named in the same sentence as ASXL2 in open-access papers (continued):
Sharing a sentence is not in itself a finding about the gene and the disease.
pediatric cancer (1 paper, 2016). "ASXL2 is a polycomb group protein with known functions in development that has also been associated with pediatric cancer, but to our knowledge has not before been suggested as a longevity gene." (PMID 27329260, 2016).
prostate carcinoma (1 paper, 2017). A carcinoma that arises from epithelial cells of the prostate gland. "Deletion and mutations in ASXL2, a chromatin/histone modifier gene that interacts with AR, are associated with castration resistant prostate cancer." (PMID 28945760, 2017).
small cell lung carcinoma (1 paper, 2024). Small cell lung cancer (SCLC) is a highly aggressive malignant neoplasm, accounting for 10-15% of lung cancer cases, characterized byrapid growth, and early metastasis. "Intriguingly, ASXL3, similar to ASXL1 and ASXL2, forms a PR-DUB complex with BAP1 but also exclusively interacts with BRD4, which binds to acetylated histones via its bromodomains in small cell lung carcinoma." (PMID 38791157, 2024). "In small cell lung cancer patients, BRD4 interacts with ASXL3 but not ASXL1 or ASXL2." (PMID 38791157, 2024).
uveal melanoma (1 paper, 2025). A melanoma derived from melanocytes of the uveal tract. "This study reveals a novel mechanism linking BAP1 expression to lipid sensitivity via ASXL2, providing insights into liver tropism and potential therapeutic avenues for metastatic uveal melanoma." (PMID 40300851, 2025).
VEXAS syndrome (1 paper, 2023). An adult-onset inflammatory disease that affects only males and is caused by somatic, not germline, mutations. "In one study, DNMT3A mutation was seen in 47.4% with VEXAS syndrome: TET2 in 20.0% and ASXL2 in 13.3%." (PMID 36879894, 2023).
cancer (11 papers, 2015 to 2024). A tumor composed of atypical neoplastic, often pleomorphic cells that invade other tissues. "ASXL2 encodes a protein serving as an epigenetic regulator and is associated with various types of cancer." (PMID 34692512, 2021). "The results of GSEA revealed that several hallmarks of cancer including epithelial mesenchymal transition, inflammatory response, and mitotic spindle were significantly enriched in the high ASXL2 expression group." (PMID 34692512, 2021). "In contrast to the aetiology of cancers associated with mutations in BAP1, mutations in ASXL1 and ASXL2 are strongly linked to myeloid cell cancers, with ~11% of haematopoietic cancers bearing ASXL1 mutations (COSMIC)." (PMID 33105797, 2020). "Beyond cancer, de novo truncating mutations in ASXL1, ASXL2, and ASXL3 have separately been identified in Bohring–Opitz, Bainbridge–Ropers, and related syndromes." (PMID 33105797, 2020). "According to the proven material, ASXL2 is related to cancer in several tissue types, such as breast, bladder, pancreas, ovary, prostate, and blood." (PMID 31888692, 2019). "The ASXL2 gene, also shown to be upregulated by VGLL1, is reported to regulate EMT transition during trophoblast differentiation and has been linked to the promotion of tumorigenesis and cell proliferation in a variety of cancer types." (PMID 38912065, 2024). "Among the top genes found by the PMN, ASXL2, BUB1B, KIF11 and TPX2 have been clinically proven to be associated with multi-cancers, which are a variety of genes commonly identified as mutated in cancers." (PMID 31888692, 2019). "Except for ASXL2 and LMO7, all these genes are reported to be frequently methylated in prostate and/or other cancers." (PMID 28945760, 2017).
tumor (10 papers, 2017 to 2025). "In a murine model studying ASXL2 loss in the context of the AML1/ETO oncofusion, ASXL2 functions as a haploinsufficient tumor suppressor when mice are challenged with either the full-length (AE) or short (AE9a) splice isoform of AML1/ETO." (PMID 34331016, 2021). "The fact that loss of even a single copy of Asxl2 promoted leukemogenesis mediated by endogenous Aml1-Eto expression strongly supports the concept that Asxl2 is a haploinsufficient tumour suppressor in the context of this subtype of AML." (PMID 28516957, 2017). "In the TWM cases, except case 1, ARID3A, ASXL1, ASXL2, FMN2, FAM83B and ZFHX4 mutations were also identified as potential oncogenic drivers, known from other tumor types." (PMID 36980598, 2023). "TIMER and CIBERSORT algorithms were employed to investigate the effect of ASXL2 on tumor microenvironment." (PMID 34692512, 2021). "We can infer that ASXL2 promotes tumor development via a variety of processes, leading to an unsatisfactory clinical outcome." (PMID 34692512, 2021). "Considering the influence of ASXL2 on tumor microenvironment, we can infer that elevated expression of ASXL2 promotes mast cells infiltration and contributes to the poor prognosis." (PMID 34692512, 2021). "Compared with the adjacent normal tissues, ASXL2 was significantly upregulated in tumor samples." (PMID 34692512, 2021). "Taken together, these findings suggest that ASXL2 may play a crucial role in the regulation of tumor microenvironment in PAAD." (PMID 34692512, 2021). "As tumor immunogenicity and immune cells may be affected by epigenomic alterations, we tried to explore the roles of ASXL2 in tumor immune microenvironment (TIME)." (PMID 34692512, 2021). "We employed GSEA and found that hallmarks of tumor such as “epithelial mesenchymal transition”, “inflammatory response” and “mitotic spindle” were dynamically correlated with the high ASXL2 expression, while “oxidative phosphorylation” was significantly enriched in the low ASXL2 expression group." (PMID 34692512, 2021). "Our study demonstrates that ASXL2 functions as a tumour suppressor to maintain normal HSC function." (PMID 28593990, 2017). "Therefore, ASXL2 functions as a tumour suppressor in myelopoiesis." (PMID 28593990, 2017). "Within our BCAC cohort, we identified 1 significantly recurrent focal deletion encompassing a 18 Mb region on chromosome 2 that included the tumour suppressor genes DNMT3A and ASXL2." (PMID 40389436, 2025). "As the expression level of ASXL2 was correlated with tumor grade and the prognosis of PAAD patients, we hypothesized that increased expression of ASXL2 promotes tumor progression." (PMID 34692512, 2021). "Finally, the protein levels of ASXL2, BAP1 and UBE2E enzymes are highly correlated in mesothelioma tumors suggesting the importance of this signaling axis for tumor suppression." (PMID 30349006, 2018). "Then, we investigate the correlation between ASXL2 expression and clinicopathological factors using logistic regression analysis and found that elevated ASXL2 expression levels in PAAD were correlated with tumor grade (G4 vs G1, P = 0.002) and ASXL2 DNA methylation (P < 0.001)." (PMID 34692512, 2021). "BAP1-ASXL2, but not ASXL1-BAP1 complexes, appears to mediate this tumor-suppressive function; overexpression of BAP1 or ASXL2, but not ASXL1, induces senescence, and deletion of the ASXM domain of ASXL2 impairs senescence (human fibroblasts IMR90 cell line)." (PMID 36068610, 2022). "Here we report that ASXL2 is required for normal haematopoiesis with distinct, non-overlapping effects from ASXL1 and acts as a haploinsufficient tumour suppressor." (PMID 28516957, 2017).
ASXL2 also shares sentences with these, for which no sentence is quoted: colon cancer (2 papers); acute leukemia (1); adenocarcinoma (1); Ataxia (1); autism (1); essential hypertension (1); fragile X syndrome (1); Insulin resistance (1); invasive ductal breast carcinoma (1); leukopenia (1); lung adenocarcinoma (1); lung carcinoma (1); Lynch syndrome (1); lysosomal storage disorders (1); mesothelioma (1); neutrophilic leukemias (1); osteopetrosis (1); T-cell acute leukemia (1); Thrombocytopenia (1).